PIK3CA (phosphatidylinositol-4,5-bisphosphate 3-kinase catalytic subunit alpha)
Diseases named in the same sentence as PIK3CA in open-access papers (continued):
Sharing a sentence is not in itself a finding about the gene and the disease.
ovarian clear cell cancer (51 papers, 2013 to 2025). An invasive malignant neoplasm that arises from the ovary and is characterized by a predominance of clear and hobnail malignant epithelial cells. "TOV21G carried mutations in ARID1A and PIK3CA, which are established drivers of ovarian clear cell carcinoma." (PMID 41228302, 2025). "PIK3CA mutations exhibit heightened prevalence in ovarian clear cell carcinoma (OCCC) and endometrioid ovarian cancer (EnOC) associated with endometriosis." (PMID 38391958, 2024). "Recent genomic research and targeted analysis have unveiled frequent mutations in the ARID1A and PIK3CA genes in ovarian clear cell carcinoma, with moderate mutations observed in PPP2R1A and KRAS." (PMID 38384812, 2024). "In another mouse model, it was observed that ARID1A and PIK3CA mutations cooperated to promote the growth of clear-cell ovarian cancer." (PMID 38646168, 2024). "Recent studies have found frequent mutations, such as ARID1A and PIK3CA, in mucinous and clear cell ovarian cancer." (PMID 37024829, 2023). "Currently, a p110alpha selective inhibitor, CYH33, is under phase 2 clinical trials (NCT05043922, jRCT2031210216), which recruits patients with clear cell ovarian carcinoma with hotspot mutations in PIK3CA." (PMID 38201563, 2023). "The patient was diagnosed with stage IC ovarian clear cell carcinoma that presented with a mutation of the phosphatidylinositol 4,5-bisphosphate 3-kinase alpha subunit (PIK3CA) gene." (PMID 36123851, 2022). "In mice models, separate ARID1A or PI3K/AKT pathway mutations promoted ovarian hyperplasia, while concomitant inactivation of ARID1A together with PIK3CA activating mutations induced tumors, similar to ovarian clear cell carcinoma (OCCC)." (PMID 36430148, 2022). "In ovarian clear-cell carcinomas, 40% of tumors harbor PIK3CA somatic mutations and the majority of these were ARID1A-deficient tumors." (PMID 35070505, 2022). "Although ovarian clear cell carcinoma was represented in a minor proportion, PIK3CA and ARID1A genes were found mutated in two of the three studied cases." (PMID 36010253, 2022). "In EOC, early genomic investigations demonstrated frequencies of genetic alterations for PIK3CA of 4%-12% (somatic mutations) in epithelial ovarian tumors, 20%-46% of clear cell ovarian cancers, 20% of endometrioid ovarian cancers, and 2.3%-3% of HGSOC." (PMID 35582310, 2021). "Molecular profiling of human endometrioid ovarian cancers revealed that the most prevalent mutations are similar to those observed in clear-cell ovarian cancer and include PIK3CA (40%), ARID1A (30%), KRAS (30%), PTEN (16%), and PPP2R1A (16%)." (PMID 32679669, 2020). "Two major genes reported to be mutated in ovarian clear cell carcinoma are PIK3CA and ARID1A, which frequently coexist with each other." (PMID 31731647, 2019). "Loss of ARID1A and PIK3CA was a common finding in 130 cases of ovarian clear cell carcinoma (56.2% and 45.0%, resp)." (PMID 29743986, 2018). "For example, a synergistic oncogenic event triggered by ARID1A loss and PIK3CA activation leads to ovarian clear cell carcinoma in an animal model." (PMID 26716708, 2015). "Furthermore, when using in vivo models of ARID1A- and PIK3CA-mutated ovarian clear cell carcinoma, treatment with an HDAC6 inhibitor reduced tumor growth and improved survival rates by promoting the activation of IFN gamma-positive CD8 T cells." (PMID 41514650, 2025). "Interestingly, we detected a previously identified hotspot for A3A mutagenesis in the helical domain of PIK3CA (c.1624G > A; c.1633G > A), which is typically associated with clear cell ovarian carcinoma." (PMID 40059825, 2025). "PIK3CA mutations are prevalent in ovarian clear cell carcinoma and endometrioid ovarian carcinoma." (PMID 35761259, 2022). "However, KRAS p.G12V was also described recently in ovarian clear cell carcinoma via whole exome sequencing, though this subtype is mainly characterized by frequent activating mutations in PIK3CA and infrequent mutations in KRAS." (PMID 31197119, 2019).
ovarian clear cell cancer (continued). "The PIK3CA gene was found to be specifically mutated in ovarian clear cell carcinoma." (PMID 27259990, 2016). "Furthermore, OVCA429 has a PIK3CA mutation, which is frequently activated in ovarian clear cell carcinomas." (PMID 26248031, 2015). "Approximately 33% of ovarian clear cell carcinoma cases exhibit co-mutations of ARID1A and PIK3CA, which activate pro-inflammatory cytokine genes via the NF-kB pathway, thereby promoting tumor growth." (PMID 41514650, 2025). "It is widely accepted that the two most frequent and important gene alterations in ovarian clear cell carcinoma occur in ARID1A and PIK3CA (both are mutated in ~ 50% of cases)." (PMID 38573494, 2024). "With regards to ovarian clear cell carcinomas, the screening for mutations in the genes of ARID1A, PIK3CA, and ZNF217, can be judged as an inadequate prognostic marker." (PMID 37548940, 2024). "In ovarian clear cell carcinoma (OCCC), PIK3CA activating mutations occur concurrently with ARID1A deletion mutations, and mutations in PIK3CA are present in 46% of ARID1A deletion tumors." (PMID 39697230, 2024). "Instead, mutations are present in genes other than HGSOC, such as ARID1A (characteristic of endometrioid and clear cell ovarian cancer) and PIK3CA (identified in clear cell ovarian cancer)." (PMID 37886943, 2023). "On the other hand, our recent studies clarified that cancer-associated genes such as ARID1A, PIK3CA and KRAS are frequently mutated not only in ovarian clear cell carcinoma but also in ovarian endometriosis." (PMID 32868822, 2020). "Specifically, in clear cell ovarian cancers, RAS mutations and c-MYC amplifications are prominent in addition to PIK3CA and PTEN alterations which is expected to lead to increased tumorigenic potential associated with “iron addiction”." (PMID 29435183, 2018). "Poorly differentiated clear-cell ovarian carcinoma develops at 7.5 weeks post-injection in AdCre;Arid1af/f;Pik3ca*H1047R female mice with 77% penetrance and with 57% of injected mice having peritoneal metastasis." (PMID 30087267, 2018). "For the study of genetically engineered mouse models, fortunately, both endometrioid and clear cell ovarian cancer have high frequency mutations in only a handful of genes: ARID1A, PIK3CA, CTNNB1, PTEN, and KRAS." (PMID 30087267, 2018). "ARID1A, PIK3CA, CTNNB1, PTEN, and KRAS are commonly mutated in both endometrioid and clear cell ovarian cancers from women." (PMID 30087267, 2018). "Previous molecular studies have indicated that mutation in PIK3CA, ARID1A, and genomic amplification of chr20q13.2 are the most common molecular genetic alterations identified in ovarian clear cell carcinoma." (PMID 27259990, 2016). "Activating mutations in PIK3CA have been described to occur in 33–40% of clear-cell ovarian cancer, and loss of PTEN expression has been found in 40% of clear-cell ovarian cancers and AKT2 amplification in 14%." (PMID 26413541, 2015). "We observed that the presence PIK3CA mutation was associated with high expression of PI3K p110α, p-Akt, mTOR in NSCLC, similar to the results from ovarian clear cell carcinoma." (PMID 24533074, 2014). "Interestingly, previous research in clear cell ovarian carcinoma (CCOC) highlighted the association of both MDM2 and PIK3CA overexpression with poor prognosis." (PMID 40149355, 2025). "These mutations were observed in both atypical and non-atypical endometriotic tissues, suggesting PIK3CA mutations as very early events in ovarian clear-cell carcinoma development." (PMID 38893278, 2024). "Drug development targeting ARID1A and PIK3CA in clear-cell ovarian carcinomas is also warranted." (PMID 38201563, 2023). "Previous studies showed that the somatic mutations of ovarian clear cell carcinoma (mainly in ARID1A, PIK3CA, KRAS and PPP2R1A) might be related to chromatin remodeling, cell proliferation, cell cycle checkpointing and cytoskeletal organization." (PMID 34680501, 2021).
ovarian clear cell cancer (continued). "The most common genetic mutations in ovarian clear cell carcinoma are adenine thymine-rich interactive domain 1A (ARID1A) and phosphatidylinositol 4,5-bisphosphate 3-kinase catalytic subunit alpha (PIK3CA) mutations, which have been identified in approximately 50% to 60% of cases." (PMID 34885229, 2021). "Notably, recent genome sequencing studies reported frequent mutations of ARID1A and PIK3CA genes and moderate mutations of PPP2R1A and KRAS in ovarian clear-cell carcinomas and frequent mutations of PTEN, CTNNB1, and KRAS in endometrioid cancer." (PMID 26413541, 2015). "More recent studies of exome sequencing performed on clear-cell ovarian cancer samples have provided definitive evidence that chromatin remodeling and PI3K are major drivers in clear cell carcinomas, with frequencies of ARID1A gene mutations of 60–65% and PIK3CA of 50–52%." (PMID 29389895, 2018). "PIK3CA is a catalytic subunit of PI3K, which is activated in ovarian clear cell carcinoma." (PMID 32595416, 2020). "Moreover, PI3K activation did not serve as a predictive marker for the sensitivity of ovarian clear cell carcinoma investigated in Japanese patients cohort to PIK3CA/AKT/mTOR inhibitors." (PMID 38391958, 2024). "PIK3CA was overexpressed in 73%, while PTEN expression was negative in 5% of the ovarian clear cell carcinomas." (PMID 31731647, 2019).
head and neck cancer (50 papers, 2012 to 2025). A primary or metastatic malignant neoplasm affecting the head and neck. "Mutation of PIK3CA usually occur in exons 9 (helical domain and 20 (kinase domain) and it has been reported in several types of cancer including head and neck cancer." (PMID 39593139, 2024). "Alterations in the PIK3CA pathway are common in HNSCC, and studies have linked PIK3CA mutations to poorer survival in patients with head and neck cancer, as well as other solid tumors." (PMID 35158773, 2022). "The prevalence of mutated PIK3CA and Akt have been estimated at 13% and 2% among head and neck cancer cell lines samples worldwide, respectively." (PMID 35631405, 2022). "PIK3CA mutations are frequently observed in various cancers including breast, colorectal, endometrial, and head and neck cancers as well as GC24." (PMID 32704014, 2020). "Somatic mutations of the PIK3CA gene have been also reported frequently in numerous cancer types including head and neck cancers." (PMID 24511546, 2014). "In particular, Lui and co-workers found a PIK3CA mutation in 30.5% of head and neck cancer patients who were sensitive to anti-mTOR treatment." (PMID 24642661, 2014). "Of these driver genes, driver mutations of PIK3CA and KEAP1/NFE2L2 have already been demonstrated to be associated with APOBEC signature enrichment, and PIK3CA variants have furthermore been demonstrated to possess high APOBEC-mutation-driven effect sizes in head and neck cancer." (PMID 35872531, 2022). "In contrast, HPV– head and neck cancers display a lower PIK3CA mutations prevalence of 15.9%." (PMID 33435133, 2021). "MET and/or PI3K pathway inhibition was assessed in NIH3T3 cells harboring MET-activating point mutation with or without ectopic expression of PIK3CAE545K and PIK3CAH1047R, as well as in MET-expressing head and neck cancer cells with endogenous PIK3CA mutations." (PMID 28532501, 2017). "In addition, a kinase domain mutation of PIK3CA (p.H1047R) was found in a head and neck cancer patient with partial response." (PMID 26859683, 2016). "The PIK3CA and SOX2 genes map at 3q26, a chromosomal region frequently amplified in head and neck cancers, which is associated with poor prognosis." (PMID 38473941, 2024). "Previous reports showed that PIK3CA mutations play a critical role in HPV-induced carcinogenesis in SCC, ACC and head and neck cancers." (PMID 37920164, 2023). "A relationship of the APOBEC mutation signature with PIK3CA E542K and E545K is also observed in HPV associated cervical and head and neck cancers." (PMID 35323317, 2022). "In ovarian, breast, and head and neck cancer, a statistically significant relationship between longer overall survival and PIK3CA positive color reaction was reported." (PMID 33287350, 2020). "In contrast, these mutations are less common in HPV-negative head and neck cancers, suggesting that APOBEC activity is the major source of PIK3CA mutations in HPV-driven carcinogenesis." (PMID 28771191, 2017). "High rates of concurrent PIK3CA mutations with PTEN loss have been documented in HPV-positive tumors, ranging from 24 to 56% in head and neck cancers to over 80% in anal cancers." (PMID 28771191, 2017). "We also performed validation experiments in the head and neck cancer cell line Cal27, which is WT for the PIK3CA gene." (PMID 28139702, 2017). "Furthermore, the expression of PIK3CA and Akt1 in head and neck cancer based on nodal metastasis status was also investigated." (PMID 41480387, 2025). "Inhibition of this pathway can also be a promising strategy, as the mutation and increased activity of PI3K catalytic subunit (PIK3CA) have been associated with resistance of tumor cells to EGFR inhibitors, and such mutation is harbored by 5–15% of head and neck cancer cases." (PMID 39408603, 2024). "Interestingly, alterations in a known head and neck cancer driver, PIK3CA, were strongly enriched in the low NF-κB group." (PMID 37523561, 2023).
head and neck cancer (continued). "This could be made possible by recent successes of PIK3CA inhibitors in a metastatic setting, with several components of this pathway deemed as promising molecular targets in head and neck cancer." (PMID 37819239, 2023). "Consistent with their prevalence in cervical squamous cell carcinomas, PIK3CA mutations are observed in 27.8% and 28.1% of cases in HPV+ head and neck cancers and anal carcinomas from the head and neck TCGA study and the anal carcinoma subset of the MSK-IMPACT cohort." (PMID 33435133, 2021). "In addition to similar histology, the HPV-positive CYLD-mutant anal carcinoma and HPV-positive CYLD-mutant head and neck carcinoma share unusually low TMB, low frequency of PIK3CA mutation, and a possible predilection for liver metastases." (PMID 32892208, 2021). "The mutational frequency of PIK3CA varied between types of HNSCC: oral squamous cell carcinomas (OSCC: 21% in cell lines and 17% in of primary tumors); nasopharyngeal carcinomas (10%;); and head and neck cancer cell lines (30%;)." (PMID 31905960, 2019). "PIK3CA is the most frequently mutated gene in HPV-positive cancers, with frequencies ranging from 6 to 42% in cervical squamous cell carcinoma, 10–42% in cervical adenocarcinoma, and 22–56% in HPV-positive head and neck cancers." (PMID 28771191, 2017). "The oncogenic properties of PIK3CA in the carcinogenesis of head and neck cancers could be described." (PMID 28127430, 2017). "Since we demonstrated altered transcriptional activity of TCF4 downstream of mutant PIK3CA in breast and head and neck cancer cells, targeting TCF4 might be new therapeutic strategy in PIK3CA mutant patients." (PMID 28139702, 2017). "Specifically, we showed that an activating PIK3CA mutation altered FOXO1 activity in the BRCA model but not in the head and neck cancer model, consistent with the context-specific predictions of our algorithm." (PMID 28139702, 2017). "In this study we have examined the impact of common PIK3CA helical and catalytic domains hotspot mutations upon MET inhibition in preclinical MET-driven and head and neck cancer models, providing therefore a first evaluation of MET targeting in the context of common PI3K mutations." (PMID 28532501, 2017). "One of such mechanisms might be upregulation of PI3K catalytic subunit (PIK3CA) as it has been evident in head and neck cancer." (PMID 22500174, 2012). "In a recent study evaluating the effect of nonsteroidal anti-inflammatory drugs (NSAID) on survival in head and neck cancer, patients with PIK3CA mutations or amplification showed prolonged disease-specific survival and overall survival with NSAID use as compared with non-NSAID users." (PMID 31905960, 2019). "Notably, in isogenic cell line models of breast cancer and head and neck cancer, we validated the altered activity of several TFs in the presence of mutant PIK3CA by measuring promoter occupancy and expression of target genes, confirming the context-specific predictions of our model." (PMID 28139702, 2017). "There are other potential biomarkers that have been studied in head and neck cancer, including EGFR, KRAS, PIK3CA, and p16INK4a protein." (PMID 36980171, 2023). "In HPV-positive head and neck cancers, significant copy number losses have been reported in 22 genes and gains in 65 genes, including RB transcriptional corepressor 1 (RB1) and PIK3CA." (PMID 28771191, 2017). "Our analysis associated mutant PIK3CA with ELK1 and TCF4 activity in both breast and head and neck cancer, and with FOXO1 activity in BRCA but not in head and neck cancer." (PMID 28139702, 2017).